ABCA4 (ATP binding cassette subfamily A member 4)
Diseases named in the same sentence as ABCA4 in open-access papers (continued):
Sharing a sentence is not in itself a finding about the gene and the disease.
retinal degeneration (continued). "Pretreatment with abn-CBD provided substantial preservation of retinal morphology in Abca4−/−/Rdh8−/− mice exposed to intense bright light, a condition that caused near-total retinal degeneration in the DMSO-treated control group, as measured by changes in the ONL thickness." (PMID 40749832, 2025). "Pathogenic or likely pathogenic variants were identified predominantly in genes already known to cause retinal degenerations (with a significant number of ABCA4 variants), although variants in genes newly identified as involved in retinal disorders were also uncovered (such as CFAP410 and GUCA1A)." (PMID 39202371, 2024). "ABCA4-associated retinal degeneration (ABCA4-RD) exhibits significant phenotypic variability." (PMID 38066771, 2023). "However, retinal degeneration became more severe in family 2 when the same mutation was associated with two ABCA4 gene mutations (p.Leu2027Phe and p.Gly1977Ser)." (PMID 32660024, 2020). "The ABCA4 gene is one of the most common disease-causing genes of inherited retinal degeneration." (PMID 33261146, 2020). "Detailed analysis of the natural history of ABCA4-associated retinal degeneration may provide an appropriate time window for intervention in further clinical trials." (PMID 33261146, 2020). "ABCA4 mutations are one of the most frequent monogenetic pathogenesis for retinal degeneration." (PMID 28890726, 2017). "There were no instances of two plausible disease-causing variants in a gene previously associated with RP, but two human retinal degeneration genes (ABCA4 and USH2A) each harbored a single plausible disease-causing variant (Thr1428Met ACG>ATG and Arg4192His CGC>CAC, respectively)." (PMID 23991284, 2013). "Therefore, analysis of ABCA4-associated retinal degeneration is difficult." (PMID 33732702, 2021). "Interestingly, our results revealed that genotype A with two null/splicing variants tended to develop RP (57%), compatible with the previous conception that RP may be the more severe phenotype in ABCA4-associated retinal degeneration." (PMID 33261146, 2020). "We validated the therapeutic potential of these compounds in 2 mouse models of retina degeneration, Abca4-/-Rdh8-/- mice, a model of acute light damage, and in an RP model, P23H Rho knock-in mice." (PMID 39808594, 2025). "To validate the therapeutic potential of JC3 and JC4 in vivo, we examined their effectiveness in 2 mouse models of retina degeneration Abca4-/-Rdh8-/- and RhoP23H/+knock-in mice." (PMID 39808594, 2025). "Cross-breeding these mice with the Rbp1−/− line resulted in Abca4−/−/Rdh8−/−/Rbp1−/− triple KO offspring that were largely protected against light-induced retinal degeneration." (PMID 40749832, 2025). "Similar to the efficacy observed with intraperitoneal injection, a single intravitreal injection of MitoTEMPO was also effective in alleviating light-induced retinal degeneration and photoreceptor ferroptosis in Abca4-/-Rdh8-/- mice." (PMID 41281747, 2025). "Triple knockout (Abca4−/−/Rdh8−/−/Rbp1−/−) mice were protected against light-induced retinal degeneration." (PMID 40749832, 2025). "Knocking out GSDME significantly attenuated light-induced photoreceptor ferroptosis and retinal degeneration in Abca4-/-Rdh8-/- mice." (PMID 41281747, 2025). "Concurrently with the genetic inactivation of the Rbp1 gene, pharmacological modulation of RBP1 activity with abnormal cannabidiol (abn-CBD) and other nonretinoid inhibitors provided substantial protection against retinal degeneration in Abca4−/−/Rdh8−/− mice." (PMID 40749832, 2025). "Collectively, these findings imply that Gsdme gene deficiency prevents retinal function decline and ameliorates light-induced photoreceptor ferroptosis and retinal degeneration in Abca4-/-Rdh8-/- mice by alleviating iron overload and lipid peroxidation." (PMID 41281747, 2025).
retinal degeneration (continued). "It has been suggested that anticonvulsants, such as tiagabine and vigabatrin, have a protective role in light-induced retinal degeneration in Abca4−/−Rdh8−/− mice, and that this protection is mediated by their role as GABA modulators." (PMID 38321543, 2024). "Exposure to bright light accelerates visual cycle disruption in Abca4−/−Rdh8−/− mice, resulting in atRAL-induced photoreceptor atrophy and retinal degeneration." (PMID 39769385, 2024). "Previous research has revealed that intense light exposure in Abca4−/−Rdh8−/− mice leads to the accumulation of atRAL in the retina, resulting in photoreceptor atrophy and retinal degeneration." (PMID 39769385, 2024). "Previous studies have shown that Abca4−/−Rdh8−/− mice develop obvious retinal degeneration after exposure to bright light compared with normal C57BL/6J mice." (PMID 39769385, 2024). "To determine the optimal injection time point, we first characterized the retinal degeneration in this Abca4-/-Rdh8-/- mouse model over a period of three months." (PMID 37852949, 2023). "The neuroprotective effect of norbixin in Abca4-/- Rdh8-/- mice during the early curative supplementation confirms our previous observations in acute blue-light induced retinal degeneration model in vivo in the same mice." (PMID 32255762, 2020). "In conclusion, short-term tests in Abca4-deficient mice, following single-dose administration and light exposure, identify IP-DHA as a therapeutic agent for the prevention of retinal degeneration." (PMID 32641711, 2020). "Abca4-/- Rdh8-/- mice are a model of STGD but also a broader model of retinal degeneration such as AMD." (PMID 32255762, 2020). "Here, we characterized the complement expression profile in ABCA4−/− retinae and aligned these findings with morphological markers of retinal degeneration." (PMID 33187113, 2020). "Mice with knockout of ATP-binding cassette subfamily A member 4 (Abca4) and retinol dehydrogenase 8 (Rdh8) genes are characterized by impaired clearing of atRAL and they were a model of light-induced retinal degeneration." (PMID 30626110, 2019). "We found that just a single dose of YC-001 protected the retinas of Abca4−/−Rdh8−/− mice from bright light-induced retinal degeneration." (PMID 29773803, 2018). "Our animals had a similar rate of retinal degeneration than the albino Abca4−∕− mice and rosette formation was only found in one 12-month-old animal from a total of 25 Abca4−∕−.Rdh8−∕− animals examined light-microscopically up to an age of 25 months." (PMID 30038866, 2018). "The retinal protection of Abca4−/−Rdh8−/− mice suggests a therapeutic potential for YC-001 in light-induced retinal degenerations." (PMID 29773803, 2018). "Notably, treatment with the mitoROS scavenger MitoTEMPO mitigated ferroptosis in atRAL-loaded photoreceptor cells and dramatically relieved photoreceptor ferroptosis and retinal degeneration in light-exposed Abca4-/-Rdh8-/- mice." (PMID 41281747, 2025). "The detrimental role of elevated cAMP is further supported by the finding that inhibition of the ADCY enzyme with SQ22536 decelerates retinal degeneration by improving rod cell survival and outer nuclear layer morphology in ovl zebrafish, rd10 and Abca4−/−Rdh8−/− mice." (PMID 40631959, 2025). "These high confidence variants were found in ABCA4, CERKL, MAK, PEX6 and RDH12 genes associated with retinal degeneration, that could be sufficient to cause pathology." (PMID 39365799, 2024). "In the same study, it was proposed that the ABCA4-mediated retinal degeneration may result from the severe lipofuscin accumulation that occurs in the RPE and that there is secondary photoreceptor degeneration due to loss of the RPE support role." (PMID 37510362, 2023). "Herein we determined whether S1R- or S2R-selective pharmacological modulation could protect photoreceptors in an AMD-related model of illumination-induced retinal degeneration in Abca4−/−Rdh8−/− mice." (PMID 36553653, 2022).
retinal degeneration (continued). "ABCA4-related retinal degeneration is genetically and clinically heterogeneous." (PMID 33732702, 2021). "However, NTPDase1, a marker of extracellular ATP levels, was elevated in the RPE/choroid of the ABCA4-/- mouse model of retinal degeneration, consistent with increased extracellular ATP levels under chronic diseased conditions." (PMID 33255431, 2020). "In this initial study, we examined whether ticagrelor lowers lysosomal pH and reduce lysosomal autofluorescence in RPE cells from the ABCA4-/- mouse model of retinal degeneration." (PMID 29725296, 2018). "Interestingly, knockout of RDH8 (retinol dehydrogenase 8) which conducts all-transretinal aldehyde metabolism together with ABCA4 showed the retinal degeneration in mice." (PMID 25922843, 2015). "Our study supports the application of the VLP platform for future research on ABCA4-related inherited retinal degenerations, providing valuable insights into disease mechanisms and facilitating pathogenicity prediction of the large number of ABCA4 genetic variants of unknown clinical significance." (PMID 39222682, 2024). "Importantly, in Abca4−/−Rdh8−/− mice, an animal model of light-induced atRAL accumulation in the retina, quercetin treatment effectively alleviated light-exposed photoreceptor atrophy and retinal degeneration by attenuating PERK signaling." (PMID 39769385, 2024). "Moreover, BIO203 administered systemically protects visual functions and retinal structure in albino rats subjected to blue-light illumination and in the retinal degeneration model of Abca4−/− Rdh8−/− double knock-out mice following 6 months of oral complementation." (PMID 36982372, 2023). "Moreover, aged ABCA4 knockout albino mice display a mild retinal degeneration." (PMID 25922843, 2015). "None of the pathogenic mutations in genes related to congenital retinoschisis (RS1) or retinal degeneration (USH2A, ABCA4, PDE6A, PDE6B, RPE65, etc.)were detected by targeted exome sequencing or WGS." (PMID 36980859, 2023). "Physiological symptoms of retinal degeneration, including RPE lipofuscin accumulation in Abca4−/− mice, and outer nuclear layer thinning in Rd16 mice, were significantly reduced in the dual-intein treated mice." (PMID 32733204, 2020). "Acute and chronic retinal degeneration following blue light damage (BLD) in BALB/c mice and aging of Abca4-/- Rdh8-/- mice, respectively, reproduce features of AMD and STGD." (PMID 32255762, 2020). "The cDNA for genes such as ABCA4 and USH2A do not fit in a single AAV, and in the USA mutations in these two genes account for 25% of families with inherited retinal degeneration." (PMID 31991730, 2020). "For inherited retinal degenerations caused by point mutations in large genes not amenable to single-adeno-associated viral (AAV) gene therapy such as USH2A and ABCA4, correcting RNA offers an alternative to gene replacement." (PMID 31991730, 2020). "By contrast, this treatment induced no retinal degeneration and only a slight ERG loss in Abca4+/+ Rdh8+/+ Rpe65-Leu450 and rd8 background mice." (PMID 27992460, 2016). "Importantly, neither Abca4−/−/Rdh8−/− nor Abca4−/−/Rdh8−/−/Rbp1−/− mice revealed spontaneous retinal degeneration without specific exposure to intense bright light." (PMID 40749832, 2025). "By contrast, BIO203 did not limit retinal degeneration in ABCA4−/− RDH8−/− mice." (PMID 36982372, 2023). "Furthermore, as reported in another study, intraperitoneal (i.p.)injection of 11-cis-6-membered-ring-retinal to Abca4-/-Rdh8-/- mice that resemble many hallmarks of AMD and its juvenile form, Stargardt disease, prior to light illumination prevented the retinal degeneration in these mice." (PMID 31835521, 2019). "In order to see whether A2E is involved in the retinal degeneration induced by BLD we used Abca4+/+Rdh8+/+ mice, in which A2E does not accumulate in RPE cells as fast as in Abca4−/− Rdh8−/− mice." (PMID 27992460, 2016).
Cone rod dystrophy (71 papers, 2005 to 2025). "This variant was previously reported in over 10 STGD1 or cone-rod dystrophy patients with compound heterozygous genotypes in the ABCA4 gene." (PMID 40606666, 2025). "Ff-ERG is an essential tool for patients with ABCA4-associated disease as it allows to distinguish the patient’s phenotype between ABCA4-associated macular dystrophy, cone dystrophy, and cone-rod dystrophy." (PMID 40643605, 2025). "Variants in ABCA4 have been associated with a range of phenotypes including macular, cone, and cone-rod dystrophy." (PMID 38219857, 2024). "Mutations in the ABCA4 gene are associated with early onset and fast-progressing cone-rod dystrophy." (PMID 36836473, 2023). "The variants in ABCA4 are associated with retina, macula, and cone-rod dystrophy, which results in vision loss." (PMID 37588055, 2023). "The ABCA4 gene encodes an ATP-binding cassette transporter in the rims of the outer segment discs, and mutations in this gene cause recessive cone-rod dystrophy and recessive Stargardt macular degeneration." (PMID 37510362, 2023). "This genotype is associated with an absent ABCA4 protein and results in early onset cone-rod dystrophy with an early and severe loss of cone photoreceptor function." (PMID 36555803, 2022). "Given the suggestive autosomal recessive cone or cone rod dystrophy pedigree, clinical diagnostic testing of the ABCA4 gene was arranged at the time, which was uninformative." (PMID 35409265, 2022). "Among the cone-rod dystrophy patients, ABCA4 was the most common mutated gene, meanwhile, USH2A was the most prevalent among the retinitis pigmentosa patients." (PMID 34327195, 2021). "Here, we present the initial results of a pilot study targeting zebrafish orthologs of five human genes linked to RP: PDE6A, PDE6B, PDE6G, ABCA4, and RHO (note, ABCA4 is also linked to cone-rod dystrophy)." (PMID 30186835, 2018). "The ABCA4 gene also was the most commonly mutated gene in cone or cone-rod dystrophy and STGD, accounting for 50% and 90% of the conclusive tests, respectively." (PMID 30374144, 2018). "The current results showed clearly that mutations in some genes cause different retinopathies, such as the CRB1 gene that causes EORD, LCA, and RP and the ABCA4 gene that causes cone or cone-rod dystrophy, EORD, and STGD." (PMID 30374144, 2018). "Four turned out to be atypical Usher syndrome: adult-onset mild neurosensorial hearing loss (RP-1735, RP-1979, RP-0338 and RP-0344 with mutations in USH2A) and one cone-rod dystrophy (CRD) (RP-1543 with mutations in ABCA4)." (PMID 26806561, 2016). "The RP-1543 family with mutations in ABCA4 was previously classified as arRP however, the presence of these two mutations arguing in favour of a cone-rod dystrophy allowed after a careful clinical evaluation its reclassification." (PMID 26806561, 2016). "Mutations in ABCA4 also result in retinitis pigmentosa and cone-rod dystrophy and have been linked to age-related macular degeneration (AMD)." (PMID 27212950, 2016). "These genes, as well as ABCA4, are also associated with clinically distinct phenotypes including retinitis pigmentosa, cone/rod dystrophy and pattern dystrophy." (PMID 24632595, 2014). "Different mutations in one gene, such as ABCA4, can have varied disease phenotypes, including macular dystrophy, cone dystrophy, cone-rod dystrophy or rod-cone dystrophy." (PMID 26237613, 2014). "ABCA4 mutations have also been identified in fundus flavimaculatus, cone-rod dystrophy, retinitis pigmentosa, and age-related macular degeneration." (PMID 19352439, 2009). "Due to the significant clinical variability of HK1-associated IRDs, which can manifest as RP, macular dystrophy or cone-rod dystrophy, even among individuals carrying the same variant, the precise contribution of ABCA4 variants remains plausible but challenging to delineate with certainty." (PMID 40269797, 2025).
Cone rod dystrophy (continued). "The importance of ABCA4 is highlighted by the finding that mutations in the gene encoding ABCA4 are responsible for autosomal recessive Stargardt disease (STGD1:MIM 248200) as well as some recessive forms of cone-rod dystrophy and retinitis pigmentosa." (PMID 33375396, 2020). "Secondly, the variant (rs1800553) from UAE S014 was described by ClinVar as “age-related macular degeneration 2, susceptibility to retinal dystrophy, inborn genetic diseases, cone rod dystrophy 3, ABCA4 Related Disorders” and has a UAE allele frequency as high as 1.9%." (PMID 32754195, 2020). "In addition, ABCA4 mutations are also responsible for retinitis pigmentosa (RP), cone-rod dystrophy (CRD), and a risk factor of age-related macular degeneration (AMD)." (PMID 33261146, 2020). "For example, partial or complete loss of ABCA4 functions cause many blinding diseases in humans including retinitis pigmentosa, cone-rod dystrophy and Stargdardt macular dystrophy, but ABCA4 KO in mice does not cause blindness unless combined with a deletion of other genes such as RDH8." (PMID 24391722, 2013). "Mutations in ABCA4 have been identified in retinitis pigmentosa (RP) and cone-rod dystrophy." (PMID 19551904, 2009). "While ABCA4 mutations are mainly studied in the context of STGD1, a subset of patients with AMD, geographic atrophy, and cone-rod dystrophies are also linked to ABCA4 variants." (PMID 41226778, 2025). "ABCA4 variants were initially associated with STGD1, a common inherited macular dystrophy, but can also cause other IRD forms, such as cone-(rod) dystrophy (CORD3) and RP (RP19)." (PMID 40269797, 2025). "While ABCA4 variants have also been associated with RP (RP19), its primary disease spectrum includes cone-rod dystrophy, with RP-like features appearing in advanced cases." (PMID 40269797, 2025). "Variation in the ABCA4 gene is the underlying cause of a spectrum of disorders, which include autosomal recessive Stargardt disease (STGD1), cone-rod dystrophy and late-onset macular dystrophy, collectively known as ABCA4-associated retinopathies." (PMID 38892127, 2024). "These include macular diseases such as age-related macular dystrophy and cone-rod dystrophies such as foveal sparing ABCA4 retinopathy and certain PRPH2 retinopathies." (PMID 35806404, 2022). "While the parents of the index family presented with rod-cone dystrophy and ABCA4-related retinopathy, their two sons revealed characteristics in the spectrum of incomplete congenital stationary night blindness and ocular albinism, respectively." (PMID 32013026, 2020). "Mutations in the ABCA4 (gene ID: 24; OMIM: 601691) gene have been described in ABCA4-associated retinopathies, including STGD1, cone-rod dystrophy (CRD), retinitis pigmentosa (RP), and retinal dystrophy." (PMID 29854428, 2018). "Apart from STGD, ABCA4 mutations have also been reported in other ocular disorders including cone-rod dystrophy and autosomal recessive retinitis pigmentosa." (PMID 25922843, 2015). "The genes involved in cone degeneration, CNGB3, CNGA3 and GNAT2, and the genes involved in cone-rod dystrophy, ABCA4, RDH5, Cord8, Cord9, RPGRIP1, GUCY2D and CRX, were all excluded from being involved in the cone-rod dystrophy described in this family of SWHD." (PMID 18593457, 2008). "Variants in the ABCA4 gene are now understood as a spectrum of phenotypes–macular dystrophy/atrophy, cone-rod degeneration, rod-cone degeneration—collectively termed ABCA4-Related Retinopathy (ABCA4R), affecting approximately 1 in 8000–10,000 individuals worldwide." (PMID 40699379, 2025). "As ABCA4 malfunction applies to STGD, types of RP, cone-rod dystrophy, and age-related macular degeneration, gene therapies to deliver functional ABCA4 may also be useful in treating several other retinal diseases." (PMID 34476420, 2020).